BIN1 (bridging integrator 1)
Diseases named in the same sentence as BIN1 in open-access papers (continued):
Sharing a sentence is not in itself a finding about the gene and the disease.
cancer (continued). "Although BIN1 deficits increase cancer-cell resistance to DNA-damaging chemotherapeutics, such as cisplatin, it is not fully understood when BIN1 deficiency occurs and how it provokes cisplatin resistance." (PMID 34948122, 2021). "For this purpose, RNF8 siRNA (si-RNF8) was transfected alone or co-transfected with si-MDC1 in BIN1-depleted cancer cells in the presence of cisplatin (2.0 μg/mL) for 72 h." (PMID 34948122, 2021). "Here, we report that the coordinated actions of MYC, PARP1, and ATM assist cancer cells in acquiring cisplatin resistance by BIN1 deficits." (PMID 34948122, 2021). "Such parallel studies are important given that actin-associated proteins are implicated in a diverse range of diseases, for example ranging from autoinflammatory disease (e.g., PSTPIP1) to cancer (e.g., BIN1)." (PMID 32164332, 2020). "By means of TWAS, we recovered seven genes (APOC1, APOE, BIN1, HMGB1, PRKAA1, SQSTM1, and UCP2) significantly associated to AD traits and some cancer models." (PMID 31608105, 2019). "In conclusion, despite the existing studies on Bin1 methylation status in some cancers, this study is the first to identify its methylation status and biological functions in ESCC." (PMID 28152502, 2017). "The results demonstrated that the low-expression rate of Bin1 was significantly higher in carcinoma tissues than in para-carcinoma tissues [70/116 (60.34%) vs. 28/116 (24.14%), P < 0.001]." (PMID 28152502, 2017). "The attenuation of Bin1 together with IDO overexpression observed in human cancers warrants further evaluation of the relationship between these two metabolic events." (PMID 26378585, 2015). "Among these 43, we found splicing events in the transcripts encoding IGFR, BIN1, RAC1 and TNC, which were extensively studied and found to exhibit a role in either tumorigenesis or cancer progression." (PMID 25908786, 2015). "Here, we provide an overview of the molecular mechanism of cisplatin-induced apoptosis and of cisplatin resistance as well as of the mechanisms by which BIN1 sensitizes cancer cells to cisplatin." (PMID 22778941, 2012). "BIN1 attenuation is frequently described in several cancers, including lung, breast and prostate cancer." (PMID 22248740, 2011). "BIN1 promoter CpG island is composed of two parts differing drastically in the methylation patterns in cancer." (PMID 17477881, 2007). "As far as BIN1 promoter contains a CpG island, DNA methylation events that affect promoter activity offer a likely mechanism for epigenetic alteration in cancer." (PMID 17477881, 2007). "Structural analysis of the human BIN1 gene has promoted characterization of its molecular pathology in cancer." (PMID 17477881, 2007). "Altered expression of the tumor suppressor BIN1 in various cancers had been previously reported in a number of papers." (PMID 17477881, 2007). "BIN1 suppresses cancer cell proliferation by promoting apoptosis in BLCA cells." (PMID 40016843, 2025). "We analyzed the protein expression levels of BIN1 across various cancers using the CPTAC dataset." (PMID 40346580, 2025). "The mechanism by which BIN1 suppresses tumors in various cancers remains unclear and has drawn our attention." (PMID 40016843, 2025). "Additionally, BIN1 regulated cancer stem cell properties through modulation of ALDH1 expression, with NOTCH2 acting as a crucial downstream mediator of ALDH1 signaling." (PMID 40016843, 2025). "Multiple studies have shown that BIN1 suppressed several cancers' development and progression." (PMID 36475339, 2023).
cancer (continued). "BIN1 staining was mainly located in the nucleus of cancer cells in EOC tissues." (PMID 35149697, 2022). "As expected, olaparib robustly activated the BIN1 gene promoter in these CDDP-R cancer cells." (PMID 34948122, 2021). "Therefore, we determined when and how the BIN1 gene expression is suppressed in the following experiments while cancer cells acquire cisplatin resistance." (PMID 34948122, 2021). "Thus, forming an ATM-phosphorylated MDC1-RNF8 protein complex is a critical determinant of cisplatin resistance in cancer cells defective in BIN1 expression." (PMID 34948122, 2021). "If ATM-phosphorylated MDC1 does not require RNF8 to mediate cisplatin resistance, we anticipated that the depletion of RNF8 alone would not change the si-MDC1-induced cisplatin sensitivity in BIN1-deficient cancer cells." (PMID 34948122, 2021). "In contrast, as predicted, the sh-BIN1 transfection did not alter the cisplatin sensitivity in BIN1-deficient cancer cell lines." (PMID 34948122, 2021). "BIN1 encodes a nucleocytosolic adapter protein of about 70 kDa and was identified for its ability to inhibit oncogenic activity of MYC by via direct interaction in a MYC domain mutated in cancer." (PMID 33801599, 2021). "Moreover, a part of the BIN1 BAR domain is also required for suppression of cancer growth, independently of c-Myc inhibition." (PMID 32164332, 2020). "By binding with c-MYC, BIN1 could significantly inhibit proliferation and apoptosis ability while induce apoptosis of cancer cells." (PMID 31496920, 2019). "It has recently been documented that Bin1 loss can promote immune escape in cancer by deregulating the immunomodulatory enzyme indoleamine 2, 3-dioxygenase (IDO); IDO inhibitors have also been found to potentiate cancer chemotherapy." (PMID 22248740, 2011). "IDO and Bin1 were detected in the cytoplasm of cancer cells and normal epithelium." (PMID 19695096, 2009). "LOH and CpG methylation analyses demonstrate that these events, being among the most widespread causes of genes' inactivation in cancer, are nevertheless not responsible for the majority of cases of BIN1 loss in BC." (PMID 17477881, 2007). "Thus, we next determined whether olaparib, a small molecule PARP1/2 inhibitor, restores BIN1 levels in the CDDP-R cancer cell lines." (PMID 34948122, 2021). "Since the BIN1 gene rarely mutates in human cancers, our results suggest that simultaneous inhibition of PARP1 and ATM provokes a new BRCAness-independent synthetic lethal effect and ultimately re-establishes cisplatin sensitivity even in platinum-refractory cancer cells." (PMID 34948122, 2021). "This study aims to elucidate the role of BIN1 in regulating BLCA cell proliferation, metastasis, and cancer stem cell properties." (PMID 40016843, 2025). "The specific aims of this study were to characterize BIN1’s expression pattern in BLCA, investigate its functional role in cancer progression, and decipher its regulatory mechanisms, particularly focusing on the ALDH1/NOTCH signaling pathway." (PMID 40016843, 2025). "As showed SRSF1 mediating the aberrant AS of BIN1 in NSCLC in our previous study, SRSF1 protein caught our attention for its role in splicing regulation in cancers." (PMID 34099633, 2021). "Because the PTEN/AKT signaling pathways adjust malignant behaviors and is frequently initiated in cancers embracing ESCC, we examined the relationship between Bin1 methylation and the key molecules of this signaling pathway by using immunoblotting studies." (PMID 28152502, 2017). "To reveal the protein expression pattern of Bin1 in ESCC patients, we detected the expression in carcinoma and para-carcinoma tissues with IHC." (PMID 28152502, 2017). "Moreover, in miR-212-3p-expressing cells, key apoptotic binding partners of c-Myc, p19ARF and Bin-1, were elevated in tandem with cleaved PARP and cleaved caspase‐3, resulting in a high apoptotic signal in cancer cells." (PMID 34922631, 2021).
cancer (continued). "We suggest that BIN1 promoter CGI, similarly to those of CDKN2A or RASSF1A genes, is composed of the two functionally unequal parts, 3' being frequently and densely methylated and 5' being lowly methylated in cancer." (PMID 17477881, 2007). "Furthermore, ectopically expressed BIN1 cDNA re-established cisplatin sensitivity in the spontaneously established CDDP-R cancer cell lines, whereas BIN1+ 12A cDNA transfection did not." (PMID 34948122, 2021). "BIN1 expression is ubiquitous in normal cells, while it is often absent in cancer cells." (PMID 33801599, 2021). "We propose that, once cancer cells spontaneously acquire cisplatin resistance, we can use a PARP inhibitor (instead of a still-controversial MYC inhibitor) to inhibit oncogenic MYC activity so that we can recover endogenous BIN1 expression and accompanying cisplatin sensitivity." (PMID 34948122, 2021). "In addition, a new mechanism has recently been revealed, in which the oncoprotein c-Myc suppresses bridging integrator 1 (BIN1), thereby releasing poly(ADP-ribose)polymerase 1, which results in increased DNA repair activity and allows cancer cells to acquire cisplatin resistance." (PMID 22778941, 2012).
myopathy (25 papers, 2009 to 2025). A disease of the muscle in which the muscle fibers do not function properly. "Subsequently, another group reported identifying a mutation at the 3′ splice acceptor site of intron 10 of BIN1 that resulted in an autosomal recessive form of a rapidly progressive and lethal myopathy in affected children." (PMID 41303468, 2025). "The recessive form of BIN1 is associated with early childhood onset, whereas the dominant form is associated with a progressive adulthood onset myopathy." (PMID 41459639, 2025). "Like human subjects harboring BIN1 coding mutations and suffering myopathy, dAmph null flies have locomotor defects, due to T-tubule morphogenesis defects in muscle cells." (PMID 34998435, 2022). "An exception is a few ARCNM cases with a splice mutation affecting the muscle-specific exon 11 of BIN1 and with childhood onset and highly progressive myopathy." (PMID 34768808, 2021). "Dnm2 knockdown was found to rescue perinatal death in Bin1 knockout mice, and to normalize t-tubule formation and muscle function in animals with myopathies caused by Bin1 mutations." (PMID 34566684, 2021). "Here, we investigated the physiological role of BIN1, a protein mutated in rare myopathies, on muscle development, function and regeneration." (PMID 32994313, 2020). "Loss of function mutations in BIN1, the gene encoding the membrane trafficking protein BIN1/amphiphysin 2, cause severe forms of myopathy with muscle weakness evident at birth." (PMID 26325203, 2015). "In this study we identified and characterized BIN1 mutations affecting the splicing of the muscle-specific exon 11, resulting in a rapidly progressing myopathy in humans and dogs." (PMID 23754947, 2013). "Our results uncover new pathophysiological mechanisms that may prove relevant to myopathies caused by Cav3 or Bin1 dysfunction." (PMID 37083699, 2023). "Moreover, human BIN1 overexpression rescued the myopathy phenotypes displayed by the Mtm1−/y mice and BIN1 function in skeletal muscles is linked to focal adhesions by controlling integrin and laminin localization." (PMID 32164332, 2020). "Also, veterinarians and veterinary pathologists should consider BIN1 mutations as a possible cause of any unexplained progressive myopathy in dogs, especially when the biopsy displays internal nuclei and lobulated or indented sarcolemma." (PMID 23754947, 2013). "It is important to note that other splicing defects, including those in BIN1 and DYS, have been previously implicated in DM1 myopathy." (PMID 38165038, 2024). "Age of onset was 3.5 years and the myopathy was highly progressive, contrasting the slow progression of muscle weakness in the reported CNM cases with BIN1 mutations in ubiquitous exons." (PMID 23754947, 2013). "Besides myoglobin, the list also included familiar proteins such as LDH and Tropomyosin alpha and included proteins that have been associated with other myopathies in TTN, MLIP and BIN1." (PMID 40110646, 2025). "Congenital myopathies with mislocalized nuclei include CNMs and are genetically heterogeneous diseases caused by mutations in at least seven genes (MTM1, DNM2, BIN1, RYR1, TTN, SPEG and ZAK), with MTM1, DNM2, BIN1 and RYR1 being the most frequently associated." (PMID 41459639, 2025). "EHBP1L1 is an integral part of RAB8 and the BIN1–dynamin complex and could thus readily explain the myopathy." (PMID 36140701, 2022). "Muscle biopsy findings in autosomal dominant BIN1-related myopathies are consistent with those found in recessive cases, with the predominance of rounded, hypotrophic type I fibres and prominent central nuclei, usually clustered in the central part of the fibre." (PMID 32456280, 2020). "Subsequently, we assessed whether this reduction was sufficient to rescue the mis-splicing of BIN1 exon 11, which has been related to myopathy and T tubule alterations, and was also found to be among the genes with higher splicing disruption in DM1." (PMID 29898953, 2018).
myopathy (continued). "Our study showing the importance of Bin1 in the maintenance of intact t-tubule structure and ([Ca2+]i) homeostasis in adult skeletal muscle could provide mechanistic insight on the potential role of Bin1 in skeletal muscle contractility and pathology of myopathy." (PMID 21984944, 2011). "In fact, BIN1- and DNM2-related myopathies affect the skeletal muscular triad, while the heart has dyads and would thus be less affected." (PMID 36140701, 2022). "This was further corroborated by identifying the splicing disruption of BIN1, a gene for which mis-splicing has been related to DM1 myopathy." (PMID 29898953, 2018). "To identify and characterize an animal model for BIN1-related CNM, we analyzed canine pedigrees with molecularly unsolved myopathies." (PMID 23754947, 2013). "Of note, exon 7 inclusion in BIN1 promoted binding to DNM2, again suggesting that the interplay between BIN1 and DNM2 is important for normal muscle function and in the setup of the CNM and DM myopathies." (PMID 32994313, 2020). "Tamoxifen might also prove useful in other myopathies where t-tubule defects secondary to increased DNM2 levels contribute to the pathogenesis, such as BIN1-related CNM and caveolin-3 and dysferlin-related myopathies." (PMID 30451843, 2018). "BIN1 acts as a negative regulator of DNM2 activity during muscle maturation and modulation of DNM2 intracellular levels alleviates the requirement for BIN1 since Bin1−/− Dnm2+/− mice were alive and did not suffer from myopathy whereas the Bin1−/− KO mice were not viable." (PMID 32164332, 2020).
neurodegenerative disease (13 papers, 2018 to 2026). A disorder of the central nervous system characterized by gradual and progressive loss of neural tissue and neurologic function. "BIN1 has been associated with neurodegenerative diseases and may be involved in neuronal function." (PMID 33076993, 2020). "The proline-rich region of the tubulin-associated unit (TAU) protein is of substantial interest in understanding neurodegenerative diseases due to its interaction with bridging integrator 1 (BIN1)." (PMID 41778964, 2026). "Overall, our in vitro studies suggest that BIN1 regulates proinflammatory responses, the expression of several neurodegenerative disease-relevant genes, and cytokine production in primary mouse microglia." (PMID 35526014, 2022). "The requirement for BIN1 to regulate Ifitm3 upregulation during inflammation has important implications for inflammatory responses during the pathogenesis and progression of many neurodegenerative diseases." (PMID 35526014, 2022). "These modules and clusters harbor known neurodegenerative disease genes including APOE, PLCG2, and BIN1." (PMID 35388616, 2022). "At the transcript level, Bin1 is highly and specifically expressed by homeostatic microglia and Bin1 down-regulation occurs as microglia adopt DAM profiles in neurodegenerative disease." (PMID 29954413, 2018). "APP/BIN1/COPS5 3xTg-AD mice are a suitable model for evaluating epigenetic changes in AD, the discovery of new epigenetic-related biomarkers for AD diagnosis, and new epidrugs for the treatment of this neurodegenerative disease." (PMID 35269588, 2022).
infection (9 papers, 2011 to 2025). The state of being infected such as from the introduction of a foreign agent such as serum, vaccine, antigenic substance or organism. "One TE (FBti0019386) affecting both Bin1 and sra was already described to be associated with gene upregulation in cold-stress conditions and in response to infection in D. melanogaster." (PMID 40826096, 2025). "The presence of RM-encoding genes may also result in a higher abundance of the phages Bin1 and Bin2 than phage Bin4, which share the same infection hosts as Bin1 and Bin2." (PMID 34479645, 2021). "This suggests, for example, targeting interaction with SH3 domain proteins such as BIN1 and CD2AP, which play redundant roles in the infection of different alphaviruses." (PMID 39556619, 2024). "In the recovered phage bins, we also identified genes related to bacterial defence systems, with 13 genes from Bin1, Bin2, and Bin3 being involved in RM, DISARM, bacteriophage exclusion system, abortive infection, Septu, or Zorya." (PMID 34479645, 2021). "We show that ADP-ribosylation factor 1 (ARF1), bridging integrator 1 (BIN1), and Rab GTPases RAB7L1 and RAB8A are important regulators of HIV-1 trafficking to the VS and therefore the infection of CD4+ T cells." (PMID 32075937, 2020). "Taken together, these data suggest that trafficking of CD81 and p24 Gag to the cell periphery to form the TEM is compromised by knockdown of ARF1, BIN-1, RAB7L1, and RAB8A, potentially preventing the efficient trans-infection of virus via the VS." (PMID 32075937, 2020). "ARF1, BIN1, RAB7L1, and RAB8A are required for HIV-1 trans-infection." (PMID 32075937, 2020). "Our preliminary validation showed that AAV(1/8)-GFP-U6-mBin1-shRNA drove substantial knock-down of Bin1 expression in hippocampal organotypic brain slices, and that control AAV(1/8)-GFP-U6-scrmb-shRNA and AAV(1/8)-GFP-U6-mBin1-shRNA infection resulted in similar distribution of GFP immunoreactivity." (PMID 31408457, 2019).
neurological disease (3 papers, 2023 to 2025). "A focused examination of six AD-related genes – APOE, APP, BIN1, CLU, MAPT and PSEN1 – and SMARCA5, which has been linked to neurological disorders, revealed different expression patterns across cell types and AD." (PMID 41255979, 2025).
respiratory diseases (2 papers, 2022 to 2025). "Correlations were evident for respiratory diseases in which APOE ε4 showed a protective tendency (OR = 0.515; p = 0.088), and BIN1 had a significative protective profile (OR = 0.556; p = 0.026)." (PMID 39081475, 2022).
psychiatric disorder (1 paper, 2025). A disorder characterized by behavioral and/or psychological abnormalities, often accompanied by physical symptoms. "Twelve lead SNPs were located within 10 genes (BIN1, TMEM106B, AP001257.1, PICALM, SLC24A4, PVRL2, APOE, CLPTM1, CTB-179K24.3, and CASS4) for AD, and all three stress-related psychiatric disorders were identified using FUMA." (PMID 39975850, 2025).